CTNNB1 (catenin beta 1)
Diseases named in the same sentence as CTNNB1 in open-access papers (continued):
Sharing a sentence is not in itself a finding about the gene and the disease.
lung carcinoma (66 papers, 2008 to 2025). "The most important finding of this study was the improved clinical outcome associated with CTNNB1 comutations when present at baseline in EGFR-driven lung cancer." (PMID 40768678, 2025). "A very recent study also reported that nuclear abnormal expression of CTNNB1 is associated with mutations of the CTNNB1 gene in lung cancer." (PMID 34465343, 2021). "Among 33 extracolonic CTNNB1 mutated cancers we detected only a single lung cancer fulfilling the criterion for a hemizygous mutation (4%)." (PMID 33115416, 2020). "Among lung cancer patients, women had a higher frequency of CTNNB1 mutations than men (3% women versus 1% men, p = 0.03)." (PMID 29156750, 2017). "Interestingly, mutation of the CTNNB1 gene seems to be uncommon in lung cancer, highlighting the aberrant stabilization of β-catenin as a critical issue in lung cancer." (PMID 37726816, 2023). "Therefore, CTNNB1 is a biomarker of recurrence undoubtedly, though the number of cases with CTNNB1 in our study is limited due to the rarity of that mutation in lung cancer." (PMID 34298845, 2021). "In our results, CTNNB1: rs1880481 with the AC/AA genotype significantly reduces the risk of developing bone metastasis, which demonstrates that CTNNB1: rs1880481 is an important SNP associated with the survival of lung cancer, highlighted here for the first time." (PMID 32453708, 2020). "Lastly, the molecular mechanism underlying the effect of CTNNB1: rs1880481 on bone metastasis of lung cancer remains unclear." (PMID 32453708, 2020). "However, poor prognosis of the CTNNB1 mutation in lung cancer has been proven in other studies." (PMID 34298845, 2021). "In addition, to further prove that JPX could upregulate β-catenin expression, we transfected siRNAs of CTNNB1, which is a gene encoding β-catenin, in lung cancer cells." (PMID 31941509, 2020). "The expression levels of the top five lung cancer genes, CTNNB1, STAT3, HIF1A, HSP90AA1, and ERBB2, were determined by comparing them with the LUAD and LUSC datasets using the GEPIA2 web server." (PMID 39113883, 2024). "We herein present the first case report of lung cancer with the co-occurrence of uncommon and complex EGFR (L858R and E709X) and CTNNB1 mutations that was successfully treated with afatinib." (PMID 36519636, 2022). "Pearson correlation analysis showed that LINC01010 was negatively correlated with EMT markers (CDH2 and CTNNB1) in lung cancer patient samples." (PMID 32518519, 2020). "Analysis of the CTNNB1 gene promoter region (−1,124–11,114 bp) revealed the presence of two CpG islands, and treatment of lung cancer cell lines with 5-Aza-CdR (7 μmol/L) for 48 h resulted in varying levels of increased β-catenin mRNA expression." (PMID 24498333, 2014). "Notably, our findings reaffirm the relevance of lung cancer genes, such as CTNNB1, STAT3, HIF1A, HSP90AA1, and ERBB2, integral to various cellular processes and pivotal in cancer genesis and advancement." (PMID 39113883, 2024). "Stromal score was positively correlated with lung cancer expression in CTNNB1 (r = 0.13, p < 0.05)." (PMID 39734333, 2024). "Combining with our data, CTNNB1 was indeed required for lung cancer with BM." (PMID 34642306, 2021). "The frequency of CTNNB1 was rare in public genomic data of Caucasian lung cancer cohorts." (PMID 34298845, 2021). "None of the 23 lung cancers with CTNNB1 mutations fulfilled the criterion for biallelic/ homozygous mutation and one tumor displayed a CTNNB1 AF of 57% and thus was scored as biallelic/homo- or hemizygous." (PMID 33115416, 2020).
lung carcinoma (continued). "Despite the small numbers in these rare lung cancer subtypes, SNV calling using the OncoMap database revealed previously undescribed SNV in FGFR1, CDKN2A, RB1, JAK3, and CTNNB1 for the large-cell type, a BRAF mutation for carcinoid, and an AKT1 mutation for adenosquamous carcinoma." (PMID 26076459, 2015). "Last, β-catenin gene CTNNB1 and TNF expression levels were positively correlated in AMs of patients with lung cancer." (PMID 37092550, 2023). "Lung cancer with complex epidermal growth factor receptor (EGFR) and CTNNB1 comutations is rare, and the efficacy of tyrosine kinase inhibitors (TKIs) is generally poor." (PMID 36519636, 2022). "Here, we encountered a lung cancer patient with complex EGFR (L858R and E709X) and CTNNB1 comutations who successfully responded to afatinib." (PMID 36519636, 2022). "Suppression of CTNNB1 downregulates its downstream transcriptional targets (c-Myc, Cyclin D1, and CDK4) and suppresses the proliferation of lung cancer cells." (PMID 33268793, 2020). "CXCR4, CK7, CDH1, CTNNB1 and HIF1A showed significant upregulation in primary lung cancer as compared to liver metastasis." (PMID 30383826, 2018). "Among them, CTNNB1, ZEB1, CDC42, HSP90AA1, BST2, PCNA, and E2F1 have all been shown to promote lung cancer progression, while SAMHD1, HRAS, and NQO1 serve as tumor suppressor genes." (PMID 28498804, 2017). "Specifically, the investigation revealed a connection between the phytochemical constituents and the genes CTNNB1, STAT3, HIF1A, HSP90AA1, and ERBB2, which have established links to lung cancer and play essential roles in the critical cellular pathways involved in disease progression." (PMID 39113883, 2024). "Further evidence for our hypothesis was determined with the indication of the following cancer stem cell markers: GABRP, CTNNB1, and MYC, which are seen in breast, colon, and lung cancer stem cells." (PMID 37370820, 2023). "Case reports of lung cancer patients with EGFR/CTNNB1 comutations are rare, and TKIs are not considered to be effective." (PMID 36519636, 2022). "Then, the abnormal occurrence of RNA editing led to abnormal expression of oncogenes, such as, CTNNB1 and FN1, thus may be responsible for the lung cancer progression." (PMID 31158229, 2019). "In lung cancer cell lines, trametinib and ICG-001 show synergy in the cell line with a Wnt-pathway (CTNNB1) mutation and not in the wild type control." (PMID 26018524, 2015). "In particular, EGFR, KRAS, CTNNB1, and ERBB2 genes were captured within the top 20% rank by at least four scRNA-seq workflows, and the two genes EGFR and KRAS, which were most common in lung cancer, were ranked in the top 5.4% and 8.9% by ZW_edgeR_Cov, respectively." (PMID 36944632, 2023).
lung carcinoma (continued). "In addition, oncogenes CTNNB1 and FN1 were highly edited and significantly overexpressed in malignantly transformed cell lines, thus may be responsible for the lung cancer progression." (PMID 31158229, 2019). "In human lung cancer, mutations have not been reported for APC and are rare in CTNNB1 (3%)." (PMID 18492263, 2008). "Quantitative gene expression patterns of CXCL12, CK7, CDH1, CTNNB1, HIF1A, MUC16, TGFBR2 and CD44v6 were analyzed from CTC, exosomes and cell free RNA of lung cancer patients with and without liver metastasis." (PMID 38877052, 2024). "CXCL12, CK7, CDH1, CTNNB1, TGFBR2 and CD44v6 were upregulated in CTC as well as cfRNA whereas all these genes were downregulated in exosomes of primary lung cancer with and without metastasis." (PMID 38877052, 2024).
prostate carcinoma (62 papers, 2010 to 2025). A carcinoma that arises from epithelial cells of the prostate gland. "Catenin (Cadherin-Associated Protein), Beta 1 (CTNNB1) genomic alterations are rare in prostate cancer (PCa)." (PMID 38907236, 2024). "Catenin (Cadherin-Associated Protein), Beta 1 (CTNNB1) genomic alterations are rare in prostate cancer (PCa), being found in ∼3–5% of the cases." (PMID 38907236, 2024). "Therapeutic resistance in prostate cancer has also been linked to CTNNB1 mutation and Wnt pathway deregulation." (PMID 35204808, 2022). "Nuclear accumulation of CTNNB1/β-catenin caused by nitric oxide (NO) leads to autophagy inhibition in prostate cancer cells." (PMID 35317831, 2022). "APC and CTNNB1 mutations are regularly found in prostate cancer." (PMID 34663878, 2021). "To test whether this increase in β-Catenin expression has a role in Pten loss-driven prostate cancer, we deleted Ctnnb1 in the Pten null model using the loxP alleles and the PBCre transgene described." (PMID 23300485, 2013). "CTNNB1 mutations in prostate cancer occur rarely, in only 5% of cases." (PMID 23300485, 2013). "We have identified targets such as AKT1, TNF, IL6, STAT3, and CTNNB1 in Osthole’s inhibition of prostate cancer, along with pathways including the TNF signaling pathway, the Interleukin-6-17 (IL-6-17) signaling pathway, and the prolactin signaling pathway." (PMID 40978029, 2025). "Further expression analysis revealed that a positive expression correlation between NR4A2 (NURR1) and CTNNB1 (β-catenin) was shown in clinical prostate cancer tissues." (PMID 38531859, 2024). "In summary, our present study demonstrates a direct role of nuclear receptor NURR1 in the promotion of both EMT and cancer stemness in prostate cancer through its direct transcriptional control of CTNNB1 and also activation of β-catenin signaling." (PMID 38531859, 2024). "Another interesting protein in this context is PAK1, which interacts with CTNNB1 and has already been described as a potential target for prostate cancer." (PMID 38927982, 2024). "Further, we found that RBM3 upregulated m6A methylation on CTNNB1 in a METTL3-dependent manner, resulting in decreased stability of CTNNB1 mRNA, thus affecting the adaptive survival of prostate cancer in the bone microenvironment." (PMID 37190171, 2023). "Although previous experiments revealed a role of CTNNB1/β-catenin in autophagy induction in prostate cancer cells, this pathway can also suppress autophagy in prostate cancer." (PMID 35317831, 2022). "For instance, primary prostate cancer patients harboring CTNNB1 genetic alterations positively correlate with earlier relapse, and CTNNB1 mutations occur at a higher frequency in plasma cell-free DNA (cfDNA) from CRPC patients that progressed on enzalutamide." (PMID 35204808, 2022). "Murine Ctnnb1-mutant prostate cancer spheroids are also reported to be enzalutamide resistant but responsive to Wnt5a loss." (PMID 35204808, 2022). "In human prostate cancer, PTEN loss is an early tumorigenic lesion, while Wnt-pathway activation through aberrations in APC, CTNNB1, RNF43, and RSPO2 are found in metastatic castration-resistant cancer, suggesting they are associated with tumor progression." (PMID 27536883, 2016). "For example, addition of indole-3-carbinol (I3C) to the culture media of a human prostate cancer cell line downregulated CTNNB1 expression." (PMID 25286307, 2014).
prostate carcinoma (continued). "Subsequently, PPI network analysis was conducted on these targets using the STRING database, which suggested that genes such as AKT1, TNF, IL6, STAT3, and CTNNB1 might be key targets for Osthole in the treatment of prostate cancer." (PMID 40978029, 2025). "Although genetic and epigenetic changes activate Wnt/β-catenin signaling to drive the progression of prostate cancer, it is not commonly observed for CTNNB1, APC, and AXIN1 genes to undergo mutations in prostate cancer." (PMID 38886806, 2024). "In the present study, we demonstrated that NURR1 could act as a key regulator in the promotion of both EMT and cancer stemness in prostate cancer through its direct transcriptional control of CTNNB1 and also activation of β-catenin signaling." (PMID 38531859, 2024). "LINC00689 involves in progression of prostate cancer by increasing CTNNB1 levels." (PMID 37025585, 2023). "Importantly, KDM4B indirectly induces autophagy via triggering nuclear translation of CTNNB1/β-catenin, leading to prostate cancer progression." (PMID 35317831, 2022). "Furthermore, we were able to identify CTNNB1, which plays a role in the development of numerous prostate cancers." (PMID 35213534, 2022). "In a prostate cancer preclinical study, LGK974 treatment is reported to significantly reduce the tumor burden and proliferation in PBCre4 Ctnnb1+/Δex3Pten+/fl mice, indicating targeting the Wnt pathway at the level of Wnt ligand secretion is efficacious against aggressive Wnt-driven prostate cancer." (PMID 35204808, 2022). "Moreover, RSPO2 gene fusions associated with elevated RSPO2 expression have been identified in prostate cancer patients, that were mutually exclusive with APC and CTNNB1 mutations." (PMID 34663878, 2021). "Many studies have suggested that the CDH1 locus (16q) and the CTNNB1 locus (3p) may harbor tumor suppressor genes for prostate cancer and bladder cancer." (PMID 27600761, 2016). "Our findings revealed that RSPO2 alterations occurred more frequently than those in other family members, as well as canonical Wnt regulators CTNNB1 and APC, providing insight into its potential significance in prostate cancer progression." (PMID 40711886, 2025). "First, network pharmacology was used to predict the potential targets of Osthole, identifying 68 targets shared with prostate cancer, including AKT1, TNF, IL6, STAT3, and CTNNB1." (PMID 40978029, 2025). "Among different subgroups in prostate cancer scRNAseq data, significant correlations between EMP1/COL3A1 and four EMT genes (VIM, SNAI2, TWIST1, and CTNNB1) were found in the osteoblast subgroup." (PMID 38187400, 2023). "Specifically, half of the “prostate cancer” pathway DEGsSD had previously been referred to in the literature (AR, CDKN1A, CTNNB1, EGFR, KLK2, NKX3-1, PDGFRA, SRD5A2)." (PMID 34768937, 2021). "We found that depending on age of prostate cancer patients and Gleason score EMT genes with distinctly altered expression are: KRT18, KRT19, MUC1 and COL4A1, CTNNB1, SNAI2, ZEB1 and MMP3." (PMID 29206234, 2017). "The list of up and downregulated genes in VEGFA165 tumours include known genes involved in neoplasia (e.g. S100A8 involved in leukaemia; S100A9 in prostate carcinoma; BCL9, CCND1 and CTNNB1)." (PMID 22045186, 2011).
prostate carcinoma (continued). "Almost all known transcription targets activated by the Wnt/β-catenin pathway, e.g. CTNNB1, CCCNDs, MMPs, PITX2, CD44, APCDD1, JUN, remain unchanged or are down-regulated in prostate cancer tissue or cell lines compared to normal tissue or cell line." (PMID 20454608, 2010). "Prostate cancer does not show an evident co-occurrence pattern, and almost all edges have a weight of 1, however, there were some central nodes including CTNNB1, RB1, and AR." (PMID 39040139, 2024). "Furthermore, half of the “prostate cancer” pathway DEGsSD are well described in the PCa literature (AR, CDKN1A, CTNNB1, EGFR, KLK2, NKX3-1, PDGFRA, SRD5A2), confirming that this is a pivotal pathway to specifically target clinical questions on canine PCa." (PMID 34768937, 2021). "β−catenin (CTNNB1) and GSK−3β are other co-regulators of Androgen receptor and phosphorylation of AR by GSK−3β which inhibit AR driven transcription, but in prostate cancer, the increase in the activity of AKT suppression of GSK−3β due to phosphorylation helps in PCa progression." (PMID 31712650, 2019). "Genomic profiling of prostate cancer patients has identified a broad range of Wnt signaling components that are genetically altered (predominantly APC and CTNNB1) and highlighted Wnt pathway components as actionable therapeutic targets that may also harbor predictive value for metastatic disease." (PMID 35204808, 2022). "Finally, the “prostate cancer” pathway also includes DEGsSD that are relatively specific to the (human) prostate (SRD5A2, KLK2, NKX3-1 and CREB3L4), proto-oncogenes (EGFR, PDGFRA, PDGFRB, NRAS) and druggable candidates (PIK3CD, CTNNB1, PIK3CG, CDKN1A)." (PMID 34768937, 2021). "The “prostate cancer” pathway also comprises genes that are relatively specific to the (human) prostate (CREB3L4, KLK2, NKX3-1 and SRD5A2), proto-oncogenes (EGFR, NRAS, PDGFRA and PDGFRB), and druggable candidates (CDKN1A, CTNNB1, EGFR, NRAS, PDGFRA, PDGFRB, PIK3CD and PIK3CG)." (PMID 34768937, 2021). "Lastly, unique hub-genes of naive CD4+ T-cells, such as HSPA8, are reported to be expressed in CD8+ T-cells in prostate cancer, while UBC, UBB, CTNNB1, and H3-3B are not reported, rendering them novel markers for naive CD4+ T-cells." (PMID 40906153, 2025).